AMOT (angiomotin)
Description:
Plays a central role in tight junction maintenance via the complex formed with ARHGAP17, which acts by regulating the uptake of polarity proteins at tight junctions. Appears to regulate endothelial cell migration and tube formation. May also play a role in the assembly of endothelial cell-cell junctions. Repressor of YAP1 and WWTR1/TAZ transcription of target genes, potentially via regulation of Hippo signaling-mediated phosphorylation of YAP1 which results in its recruitment to tight junctions.
Synonyms: KIAA1071
Tractability: Small molecule: a structure with a bound ligand is known. Antibody: its Gene Ontology location is reachable by antibodies, with medium confidence. PROTAC: UniProt records ubiquitination sites on it; ubiquitination databases record sites on it; its protein half-life has been measured.
Gene: Protein-coding gene on chromosome X (112,774,503 to 112,840,831, reverse strand). Ensembl gene ENSG00000126016.
Subcellular location: Cell junction, tight junction
Subcellular location (Human Protein Atlas): Cell Junctions; Nucleoplasm
Pathways (Reactome):
Cell-Cell communication: Regulation of CDH11 function
Signal Transduction: Signaling by Hippo
Gene Ontology:
Molecular function: angiostatin binding; protein binding; signaling receptor activity
Biological process: hippo signaling; negative regulation of angiogenesis; negative regulation of transcription by RNA polymerase II; regulation of cell migration; actin cytoskeleton organization; angiogenesis; establishment of cell polarity involved in ameboidal cell migration; regulation of modification of postsynaptic actin cytoskeleton
Cellular component: actin filament; cell junction; COP9 signalosome; endocytic vesicle; external side of plasma membrane; lamellipodium; ruffle; bicellular tight junction; cytoplasmic vesicle; cytosol; plasma membrane; glutamatergic synapse; postsynaptic density
Homologues: Orthologues: chimpanzee AMOT (99% identical), macaque AMOT (98% identical), pig AMOT (94% identical), rabbit AMOT (93% identical), dog AMOT (91% identical), guinea pig AMOT (90% identical), rat Amot (88% identical), mouse Amot (87% identical), tropical clawed frog amot (59% identical), zebrafish amot (52% identical). Paralogues in human: AMOTL1 (44% identical), AMOTL2 (32% identical).
Diseases named in the same sentence as AMOT in open-access papers:
AMOT is named in the same sentence as 39 diseases in open-access papers, as found by Europe PMC text mining. Sharing a sentence is not in itself a finding about the gene and the disease. The quoted sentences say what the papers report.
breast carcinoma (17 papers, 2006 to 2021). "Here, we report for the first time the aberrant expression of angiomotin in breast tumours, its correlation with angiogenesis and association with metastatic disease in patients with breast cancer." (PMID 16430777, 2006). "Here we report that angiomotin, a protein that regulate the motility and morphology of endothelial cells is highly expressed in human breast tissues and that its levels are associated with other angiogenic markers and with the clinical outcome in patients with breast cancer." (PMID 16430777, 2006). "miR-205 is discovered to be a suppressor factor in breast cancer, which can target E2F transcription factor 1, angiomotin, and other genes, and then to reduce cell proliferation, inhibit invasion, and increase apoptosis." (PMID 34306321, 2021). "AMOT has previously been reported as an oncogene in breast cancer which promotes migration and angiogenesis." (PMID 32854238, 2020). "In breast cancer, hsa-miR-205-5p directly inhibits AMOT by binding to its 3′-untranslated region (3′-UTR)." (PMID 31848596, 2019). "Studies have shown that AMOT activates the ERK1/2 pathway to drive cell proliferation in ER+ breast cancer, and that miR-205-5p inhibits cell growth by direct targeting of AMOT in MCF-7 breast cancer cells." (PMID 31752366, 2019). "According to GENT database, AMOT expression showed up-regulated in colon cancer and lung cancer while it is down-regulated in breast cancer, kidney cancer, head and neck tumor when comparing to correspondingly normal control tissues." (PMID 29650031, 2018). "In breast cancer, AMOT was observed to be highly expressed in cancer tissues comparing with adjacent non-cancerous tissues." (PMID 29650031, 2018). "Recent data has shown Angiomotin to be highly expressed in breast cancer tissue and to be important for promoting breast cancer cell proliferation and invasion." (PMID 28650989, 2017). "In breast cancer, AMOT was proposed to coordinate the dysregulation of cell polarity with the induction of neoplastic growth." (PMID 28052036, 2017). "The role of angiomotin in endothelial cell migration and its correlation with poor survival in breast cancer patients suggest that it is a potential target for anti-angiogenic immunotherapy." (PMID 21385454, 2011). "Although it is at early stage in the investigation of angiomotin and its family into breast cancer, the current study and recent reports have clearly shown the important role of angiomotin in angiogenesis and in the aggressive nature of breast tumours." (PMID 16430777, 2006). "Breast cancer tissues expressed significantly higher levels of angiomotin transcript, compared with normal mammary tissues (33.1 ± 11 in normal versus 86.5 ± 13.7 in tumour tissues, p = 0.003)." (PMID 16430777, 2006). "For example, AMOT appears to regulate breast cancer cell proliferation and invasion." (PMID 27902487, 2017). "AMOT is highly expressed in breast cancer and promotes the cancer cell proliferation and invasion." (PMID 28071680, 2017). "Angiomotin is a motility regulator of vascular endothelial cells and may be a molecule that links to breast cancer growth and spread by way of stimulating angiogenesis." (PMID 16430777, 2006). "In addition to the lipid metabolism markers, the MRD islets of patient 1016 also showed modulation of genes, such as AMOT, belonging to a dormancy signature previously identified in breast cancer, suggesting the presence of a subpopulation of more quiescent cells within the captured MRD sample." (PMID 33945502, 2021). "Among many, angiomotin (AMOT) and Endoplasmic Reticulum Protein 29 (ERp29) are the direct targets for miR-205 in breast cancer and miR-205 binds to the 3′ UTR site of both genes." (PMID 32854238, 2020). "AMOT was recently found to play important roles in neurofibromatosis type 2 (NF2), breast cancer, and renal cell carcinoma." (PMID 28052036, 2017).
breast carcinoma (continued). "Although tumours from patients with local recurrence and who died of breast cancer also had a higher level of angiomotin, the difference was nonetheless not significant." (PMID 16430777, 2006).
lung carcinoma (9 papers, 2016 to 2025). "In clinical lung cancer specimens, AMOT expression was found to be significantly decreased, which indicated its tumor suppressive role." (PMID 29650031, 2018). "Interestingly, the RNA-Seq analysis identified genes that are strongly upregulated in the absence of FIH under both normoxia and hypoxia, including angiomotin (Amot), a known regulator of cell migration and proliferation in lung cancer." (PMID 37707961, 2023). "AMOT was significantly downregulated in lung cancer tissues and tumor cells." (PMID 33658392, 2021). "Moreover, it was recently reported that TAZ and CYR61 were implicated in lung cancer progression and EMT via angiomotin." (PMID 27583562, 2016). "AMOT, a scaffold protein that sequesters YAP and TAZ into the cytoplasm, inhibiting their nuclear function, has been shown to decrease lung cancer progression in vitro while its knock-down increases lung cancer growth and metastasis in vivo, and is significantly reduced in lung cancer specimens." (PMID 29734788, 2018).
osteosarcoma (8 papers, 2016 to 2024). A usually aggressive malignant bone-forming mesenchymal neoplasm, predominantly affecting adolescents and young adults. "In osteosarcoma, SNHG12 causes increased cell proliferation and migration as well as stimulated angiogenesis, through up-regulation of AMOT (angiomotin)." (PMID 32318335, 2020). "The amplification of the expression of the angiomotin (AMOT) gene in cells from human osteosarcomas by SNHG12 also has been reported to accelerate cellular replication and migration, while the knockdown of SNHG12 had the opposite consequence but failed to influence programmed cell death." (PMID 39015175, 2024). "For example, SNHG12 could facilitate the proliferation and migration of human osteosarcoma cells by up-regulating angiomotin gene expression." (PMID 33009370, 2020). "In cells from human osteosarcomas, oncogenic lncRNA SNHG12 additionally impacts cellular replication through angiomotin gene expression amplification." (PMID 39015175, 2024).
gastric cancer (4 papers, 2020 to 2023). A primary or metastatic malignant neoplasm involving the stomach. "The association of YAP and ZO-1 is mediated by angiomotin (AMOT) in gastric cancer cells." (PMID 36362947, 2022). "In gastric cancer, the absence of CLIC1 impedes invasion and migration, likely by increasing the expression of AMOT-p130." (PMID 38027011, 2023).
liver cancer (3 papers, 2017 to 2025). An epithelial or non-epithelial malignant neoplasm that arises from the liver. "In sum, TPA has been established as an anti-tumorigenic drug in liver cancer cells via YAP and AMOT." (PMID 28322318, 2017). "Here, we sought to determine whether the TPA-reduced transformative phenotypes in liver cancer cells depend on YAP and AMOT." (PMID 28322318, 2017). "However, which PKC isoform mediates TPA-induced simultaneous translocation of AMOT and YAP from the nucleus to cytoplasm in liver cancer cells remains unknown and must be investigated in future studies." (PMID 28322318, 2017).
ovarian carcinoma (3 papers, 2018 to 2020). A malignant neoplasm originating from the surface ovarian epithelium. "It has been confirmed that seRNA from urothelial cancer associated 1 (UCA1) promotes ovarian cancer development through interacting with angiomotin (AMOT) to activate yes-associated protein (YAP) signaling." (PMID 32278350, 2020).
endometrial cancer (2 papers, 2017 to 2019). Primary or metastatic malignant neoplasm involving the endometrium (mucous membrane that lines the endometrial cavity). "Identification of the crosstalk between AMOT/Merlin pathway and Rac/Rich1 pathway is considered to contribute to the elucidation of the malignant transformation mechanisms of endometrial cancer." (PMID 31330820, 2019). "Taken together, our findings indicated that the loss of LSR promoted cell invasion and migration via upregulation of AREG dependent on YAP/pYAP and AMOT/Merlin in human endometrial cancer cells." (PMID 28071680, 2017). "The loss of LSR promoted cell invasion and migration via upregulation of TEAD1/AREG dependent on YAP/pYAP and AMOT/Merlin in human endometrial cancer cells." (PMID 28071680, 2017). "In endometrial cancer, decreased expression of AMOT was observed during cancer progression." (PMID 31330820, 2019). "However, it is necessary to investigate the relationship between LSR and AMOT/Merlin at tricellular contacts and the roles of AMOT/Merlin in human endometrial cancer cells in more detail." (PMID 28071680, 2017). "Thus it appears that the loss of LSR in part promoted cell invasion and migration via AMOT/Merlin in human endometrial cancer cells." (PMID 28071680, 2017). "Furthermore, the expression of LSR and AMOT was decreased in G2 and G3 endometrial cancers compared to G1." (PMID 28071680, 2017). "In endometrial cancer diagnosed as the classic endometrial type I (endometrioid), LSR and AMOT were highly expressed in some cancer cells that formed gland-like structures." (PMID 28071680, 2017).
Hypertension (2 papers, 2017). The presence of chronic increased pressure in the systemic arterial system. "Given the role of vascular-endothelial dysfunction in the mechanisms of developmentally programmed hypertension, these findings suggest that the pro-angiogenic gene AMOT is involved and may have an important role in the development of the vascular system." (PMID 29036193, 2017). "Subgroup analyses revealed that AMOT P130 protein expression was increased in OSA patients with excessive daytime sleepiness, BIRC3 protein expression was decreased in OSA patients with hypertension, and LGALS3 protein expression was increased in OSA patients with chronic kidney disease." (PMID 28520763, 2017). "Moreover, we verified AMOT, PLEKHH3, ADAR, BIRC3, and LGALS3 protein over-expressions in the treatment-naïve OSA patients, and discovered a correlation between AMOT/BIRC3/LGALS3 protein expression and the presence of EDS/hypertension/CKD, respectively." (PMID 28520763, 2017). "AMOT and GALIG may constitute an important determinant for the development of hypersomnia and kidney injury, respectively, while BIRC3 may play a protective role in the development of hypertension." (PMID 28520763, 2017).
Alzheimer disease (1 paper, 2024). A progressive, neurodegenerative disease characterized by loss of function and death of nerve cells in several areas of the brain leading to loss of cognitive function such as memory and language. "All of these genes are known to be involved in neurological diseases; AMOT is implicated in Alzheimer’s disease and PAK3 is associated with inherited X-linked intellectual disability." (PMID 38764741, 2024).
atrial fibrillation (1 paper, 2025). A disorder characterized by an electrocardiographic finding of a supraventricular arrhythmia characterized by the replacement of consistent P waves by rapid oscillations or fibrillatory waves that vary in size, shape and timing and are accompanied by an irregular ventricular response. "A recent study validated a set of five differentially expressed and co-upregulated genes (DEGs) (DGAT1, AMOT, PDE11A, TYMS, and TMEM98) that were elevated in patients with atrial fibrillation, liver disease, and atrial fibrillation associated with liver disease compared to healthy controls." (PMID 40141794, 2025).
autism (1 paper, 2025). Persistent deficits in social interaction and communication and interaction as well as a markedly restricted repertoire of activity and interest as well as repetitive patterns of behavior. "Defective AMOT protein causes synapse developmental defects, leading to CNS disorders such as autism." (PMID 40833988, 2025).
breast tumour (1 paper, 2006). "Angiomotin, a putative endothelial motility factor, is highly expressed in human breast tumour tissues and linked to angiogenesis." (PMID 16430777, 2006). "A quantitative analysis of the molecules indicated that there was a significantly higher level of angiomotin in breast tumour tissues, than in normal tissues." (PMID 16430777, 2006). "This study examined the expression of angiomotin and its analogues, angiomotin-like 1 (L1) and -like 2 (L2) in breast tumour tissues, and analysed their correlation with angiogenesis and clinical outcomes." (PMID 16430777, 2006). "We examined the expression of angiomotin and its analogue molecules angiomotin-like-1 and like-2 in a cohort of breast tumours against the clinical information." (PMID 16430777, 2006). "There are no consistent patterns to suggest these two analogues of angiomotin are also linked to the aggressiveness of breast tumours, although both of the angiomotin related proteins are expressed in endothelial cells." (PMID 16430777, 2006).
chordoma (1 paper, 2023). Chordomas are rare malignant tumors arising from embryonic remnants of the notochord in axial skeleton. "The expression of AMOT, RYR3, P2RX5, and TNFSF14 were higher in recurrent chordomas than primary chordomas while NPTX1 was contrast." (PMID 38012562, 2023). "miR-186-5p, miR-125b-5p, miR-1260a, and their target protein mRNAs including AMOT, NPTX1, RYR3, P2RX5, TNFSF14 may be the basement of chordoma research." (PMID 38012562, 2023).
colorectal cancer (1 paper, 2026). A primary or metastatic malignant neoplasm that affects the colon or rectum. "In colorectal cancer (CRC) cells, basroparib increased AMOT protein abundance, promoted AMOT-YAP complex formation, and enforced cytoplasmic sequestration of YAP, thereby dampening YAP-dependent transcription." (PMID 41569232, 2026).
congenital hydrocephalus (1 paper, 2025). Hydrocephalus that is present at birth. "In summary, the identified AMOT pathogenic variant is associated with congenital hydrocephalus, which becomes evident only in the third trimester of gestation." (PMID 40892511, 2025). "AMOT encodes a tight junction protein, and its malfunction is expected to perturb barrier permeability of polarized cells, in agreement with the finding of congenital hydrocephalus in the patients." (PMID 40892511, 2025). "In line with this knowledge, we have shown here that the increased stability of the newly identified AMOT mutant is 1 of the crucial reasons for development of congenital hydrocephalus." (PMID 40892511, 2025).
HIV-1 infection (1 paper, 2015). The type species of lentivirus and the etiologic agent of acquired immunodeficiency syndrome (AIDS). "T cells are natural hosts for HIV-1 infection, and AMOT mRNA is present in these cells, including Jurkat T cells." (PMID 25633977, 2015). "AMOT mRNA is expressed in 293T cells, as well as in white blood cells and lymphoid tissues that are the natural hosts for HIV-1 infection." (PMID 25633977, 2015).
Hydrocephalus (1 paper, 2025). Hydrocephalus is an active distension of the ventricular system of the brain resulting from inadequate passage of CSF from its point of production within the cerebral ventricles to its point of absorption into the systemic circulation. "We identified a genetic mutation in the AMOT gene linked to inherited hydrocephalus, revealing how disrupted protein regulation may impair brain development and barrier function." (PMID 40892511, 2025).
metastatic disease (1 paper, 2006). "Third, significantly higher levels of angiomotin transcript are seen in patients with metastatic disease." (PMID 16430777, 2006). "The levels of angiomotin in tumours from patients who had metastatic disease were also significantly higher than those patients who remained disease free (p = 0.03)." (PMID 16430777, 2006).
myocardial infarction (1 paper, 2021). Gross necrosis of the myocardium, as a result of interruption of the blood supply to the area, as in coronary thrombosis. "Altogether, the involvement of sCD146 and AMOT in angiogenesis and tissue regeneration in post-ischemic situations and the high AMOT expression in neovascular endothelial cells during angiogenesis makes AMOT an ideal target for imaging of the myocardial infarction healing process." (PMID 34571954, 2021).
neurofibromatosis (1 paper, 2017). A hereditary neoplastic syndrome in which tumors grow in the nervous system. "Angiomotin (AMOT) is a family of proteins found to be a component of the apical junctional complex of vertebrate epithelial cells and is recently found to play important roles in neurofibromatosis type 2 (NF-2)." (PMID 28052036, 2017).
preeclampsia (1 paper, 2021). Preeclampsia is a hypertensive disorder of pregnancy that is characterized by new-onset hypertension with proteinuria presenting after 20 weeks of gestation, and depending on mild or severe forms may initially present with severe headache, visual disturbances, and hyperreflexia. "We observed a decreased expression of angiopoietin-1 and angiomotin in IUGR-ECFCs, as reported in pregnancies complicated by preeclampsia with IUGR, in endothelial cells from knockdown angiomotin zebrafish, and also during the postnatal period in ECFCs from low-birth-weight newborns." (PMID 34576323, 2021).